PLEKHA4 (pleckstrin homology domain containing A4)
Diseases named in the same sentence as PLEKHA4 in open-access papers (continued):
Sharing a sentence is not in itself a finding about the gene and the disease.
tumor (continued). "To better understand the relationship between PLEKHA4 and tumor-immune system in LGG, we examined the role of PLEKHA4 in immune infiltration using the ESTIMATE, ssGSEA, as well as the TIMER algorithms." (PMID 37818357, 2023). "The high PLEKHA4 protein level was significantly correlated with age,WHO grade and Ki67, IDH satus, and tumor size (P < 0.05)." (PMID 36714030, 2023). "This study shows a potential correlation between the expression of PLEKHA4, the prognosis of LGG patients, and the tumor immune microenvironment." (PMID 36408463, 2022). "Multiple bioinformatic tools, including Tumor Immune Estimation Resource (TIMER), Gene Expression Profiling Interactive Analysis (GEPIA2), Shiny Methylation Analysis Resource Tool (SMART), etc., were incorporated to analyze the PLEKHA4." (PMID 37818357, 2023). "The synthetical analysis of CpG methylation and PLEKHA4 performed better than any single index in predicting OS of LGG patients, indicating that these CpG sites can aid LGG tumor progression monitoring and serve as prognostic markers as well, to identify patients with “high-risk”." (PMID 37818357, 2023). "Finally, the prognostic significance of PLEKHA4 related to OS, PFI, and DSS was verified using the independent TCGA cancer cohort with 9,163 tumor samples via univariate Cox regression analysis." (PMID 36408463, 2022). "The high expression of PLEKHA4 is often accompanied by IDH nonmutation, 1p/19q noncoding, higher tumor grade, and patient age." (PMID 36408463, 2022).
cancer (5 papers, 2021 to 2024). A tumor composed of atypical neoplastic, often pleomorphic cells that invade other tissues. "In particular, PLEKHA4 expression is significantly correlated with the infiltration of cancer associated fibroblast, which can secrete chemokines and cytokines that promote tumorigenesis." (PMID 37818357, 2023). "The expression levels of PLEKHA4 in 33 types of cancer in the TCGA (The Cancer Genome Atlas) database were collected via the UCSC Xena browser." (PMID 36714030, 2023). "Pan-cancer analysis were further carried out, and results showed that PLEKHA4 was dysregulated in majority of cancer types." (PMID 37818357, 2023). "At first, we compared the mRNA expression of PLEKHA4 in 20 types of cancer with that in normal tissues through Oncomine databases." (PMID 36714030, 2023). "Given the limited number of studies on PLEKHA4 in cancer, we evaluated PLEKHA4 levels in 33 solid tumors, including LGG." (PMID 36408463, 2022). "The results show that PLEKHA4 is closely correlated with the immune microenvironment of multiple cancers, including LGG." (PMID 36408463, 2022). "PLEKHA4 mRNA levels were significantly higher in most cancers than in normal tissues." (PMID 36408463, 2022). "Rs4801778-T (PLEKHA4), rs11919389-C (ZBTB11), rs13050728-C (IFNAR2), and rs10774671-A (OAS1) exhibited a positive or negative regulation in TULP2, HSD17B14, LOC285359, LOC100009676, SENP7, IFNAR2, OAS3, and OAS1 in multiple cancer types." (PMID 35082790, 2021).
PLEKHA4 also shares sentences with these, for which no sentence is quoted: COVID-19 (2 papers); thyroid carcinoma (2); acute myeloid leukemia (1); adrenocortical carcinoma (1); bladder cancer (1); breast invasive carcinoma (1); breast tumor (1); central nervous system neoplasm (1); colon adenocarcinoma (1); diffuse large B-cell lymphoma (1); esophageal carcinoma (1); head and neck cancer (1); immune dysfunction (1); lung adenocarcinoma (1); lung carcinoma (1); lung squamous cell carcinoma (1); microcephaly (1); ovarian carcinoma (1); ovarian serous cystadenocarcinoma (1); prostate adenocarcinoma (1); respiratory failure (1); schizophrenia (1); skin cutaneous melanoma (1); stomach adenocarcinoma (1); testicular germ cell tumor (1); thymoma (1); uterine corpus endometrial carcinoma (1).